Y_RNA (Y RNA )
Gene: Miscellaneous RNA gene on chromosome 1 (185,630,428 to 185,630,528, reverse strand). Ensembl gene ENSG00000207108.
Homologues: Orthologues: macaque Y_RNA (89% identical). Paralogues in human: Y_RNA (90% identical), RNY3P14 (89% identical), Y_RNA (89% identical), RNY3 (88% identical), Y_RNA (88% identical), RNY3P1 (87% identical), Y_RNA (87% identical), Y_RNA (86% identical), Y_RNA (85% identical), RNY3P11 (84% identical), Y_RNA (84% identical), RNY3P9 (83% identical), and 92 more.